CCT7P1 (chaperonin containing TCP1 subunit 7 pseudogene 1)
Synonyms: CCT7-2P
Gene: Processed pseudogene on chromosome 6 (149,879,962 to 149,881,572, forward strand). Ensembl gene ENSG00000217733.
Diseases named in the same sentence as CCT7P1 in open-access papers:
CCT7P1 is named in the same sentence as 1 disease in open-access papers, as found by Europe PMC text mining. Sharing a sentence is not in itself a finding about the gene and the disease. The quoted sentences say what the papers report.
tumour (1 paper, 2022). "In contrast, the HRs of CCT7P1 and NPY6R were less than 1, suggesting that they may inhibit tumour progression." (PMID 36127676, 2022).